EXT1 (exostosin glycosyltransferase 1)
Description:
Glycosyltransferase forming with EXT2 the heterodimeric heparan sulfate polymerase which catalyzes the elongation of the heparan sulfate glycan backbone. Glycan backbone extension consists in the alternating transfer of (1->4)-beta-D-GlcA and (1->4)-alpha-D-GlcNAc residues from their respective UDP-sugar donors. Both EXT1 and EXT2 are required for the full activity of the polymerase since EXT1 bears the N-acetylglucosaminyl-proteoglycan 4-beta-glucuronosyltransferase activity within the complex while EXT2 carries the glucuronosyl-N-acetylglucosaminyl-proteoglycan 4-alpha-N-acetylglucosaminyltransferase activity. Heparan sulfate proteoglycans are ubiquitous components of the extracellular matrix and play an important role in tissue homeostasis and signaling.
Synonyms: ttv; EXT; LGCR; LGS; TRPS2
Tractability: Small molecule: a structure with a bound ligand is known. Antibody: UniProt predicts a signal peptide or a membrane-spanning region. PROTAC: ubiquitination databases record sites on it; its protein half-life has been measured.
Gene: Protein-coding gene on chromosome 8 (117,794,490 to 118,111,826, reverse strand). Ensembl gene ENSG00000182197.
Subcellular location: Golgi apparatus membrane; Golgi apparatus, cis-Golgi network membrane; Endoplasmic reticulum membrane
Pathways (Reactome):
Disease: Defective EXT1 causes exostoses 1, TRPS2 and CHDS; Defective EXT2 causes exostoses 2
Metabolism: HS-GAG biosynthesis
Gene Ontology:
Molecular function: glucuronosyl-N-acetylglucosaminyl-proteoglycan 4-alpha-N-acetylglucosaminyltransferase activity; N-acetylglucosaminyl-proteoglycan 4-beta-glucuronosyltransferase activity; protein binding; protein heterodimerization activity; protein homodimerization activity; acetylglucosaminyltransferase activity; glucuronosyltransferase activity; heparan sulfate N-acetylglucosaminyltransferase activity; glycosyltransferase activity
Biological process: glycosaminoglycan biosynthetic process; heparan sulfate proteoglycan biosynthetic process; ossification; polysaccharide biosynthetic process; glycoprotein biosynthetic process
Cellular component: catalytic complex; endoplasmic reticulum; endoplasmic reticulum membrane; Golgi apparatus; Golgi membrane; UDP-N-acetylglucosamine transferase complex; membrane
Genetic constraint (gnomAD): Loss-of-function variants: 20 observed, 85.82 expected, observed/expected ratio (o/e) 0.23, 90% interval 0.16 to 0.34. The upper end of that interval is the gene's LOEUF score, 0.34, which puts it in group 1 of 6, group 1 being the genes least tolerant of losing a copy. Missense variants: 755 observed, 990.94 expected, observed/expected ratio (o/e) 0.76, 90% interval 0.72 to 0.81. Synonymous variants: 348 observed, 374.34 expected, observed/expected ratio (o/e) 0.93, 90% interval 0.85 to 1.02.
Gene-disease validity (ClinGen):
ClinGen rates the evidence that EXT1 causes each of these diseases.
exostoses, multiple, type 1 (autosomal dominant): Definitive. Any exostoses, multiple in which the cause of the disease is a mutation in the EXT1 gene.
Homologues: Orthologues: chimpanzee EXT1 (99% identical), macaque EXT1 (99% identical), mouse Ext1 (99% identical), rat Ext1 (99% identical), pig EXT1 (99% identical), rabbit EXT1 (99% identical), guinea pig EXT1 (98% identical), dog EXT1 (91% identical), tropical clawed frog ext1 (89% identical), zebrafish ext1b (84% identical), zebrafish ext1a (83% identical). Paralogues in human: EXTL1 (42% identical), EXT2 (33% identical), EXTL3 (30% identical), EXTL2 (13% identical).
Diseases named in the same sentence as EXT1 in open-access papers:
EXT1 is named in the same sentence as 126 diseases in open-access papers, as found by Europe PMC text mining. Sharing a sentence is not in itself a finding about the gene and the disease. The quoted sentences say what the papers report.
Osteochondroma (46 papers, 2008 to 2026). A common, benign cartiliginous neoplasm arising from the metaphysis of bone. "Mutations in the EXT1 gene can lead to a condition called hereditary multiple exostoses, which is characterized by the formation of benign bone tumors called osteochondromas." (PMID 38886662, 2024). "The variability in the clinical presentation of HME, such as the number and size of osteochondromas, can be attributed to the different mutations within the EXT1 and EXT2 genes." (PMID 39057136, 2024). "No significant change in uACR was observed in Ext1(ECKO), consistent with data from multiple osteochondroma (MO) patients, an autosomal dominant disease resulting from loss of function in EXT1 or EXT2." (PMID 38302978, 2024). "Patients with EXT1 mutations often exhibit more severe phenotypes, including a higher number of osteochondromas, greater limb deformity, and a higher risk of malignant transformation compared to those with EXT2 mutations." (PMID 39057136, 2024). "This patient suffered from multiple osteochondromas, an autosomal dominant disease caused by mono-allelic germline mutations in the EXT1 or EXT2 gene." (PMID 35103870, 2022). "Many studies have shown that the etiology of osteochondroma is largely due to genomic mutations in EXT1 and EXT2, resulting in the loss or insufficient synthesis of glycosyltransferases which are related to HS synthesis." (PMID 36360300, 2022). "Hereditary Multiple Exostoses (HME) is a rare autosomal disorder characterized by the presence of multiple exostoses (osteochondromas) caused by a heterozygous loss of function mutation in EXT1 or EXT2; genes involved in heparan sulfate (HS) chain elongation." (PMID 34815940, 2021). "Exostosin glycosyltransferase 1 (EXT1), an endoplasmic reticulum transmembrane protein that frequently mutated in multiple osteochondromas, acts as a connector between NOTCH1 and FBXW7." (PMID 33822486, 2021). "The EXT1 and EXT2 genes have been identified for MO, especially in the context of the loss of the remaining EXT1 wild type allele that was demonstrated in hereditary osteochondromas." (PMID 31842965, 2019). "Some research has shown that knockdown of EXT1 mRNA expression in osteochondromas was associated with intracellular accumulation of HSPGs in the Golgi apparatus." (PMID 31842965, 2019). "We found previously that the onset of osteochondroma formation in conditional Ext1-deficient mice is accompanied by ectopic expression of phosphorylated SMAD1/5/8 proteins in perichondrium that mediate canonical BMP signaling and are pro-chondrogenic." (PMID 28445472, 2017). "Multiple osteochondroma (MO) is an autosomal dominant skeletal disorder characterized by the formation of multiple osteochondromas, and exostosin-1 (EXT1) and exostosin-2 (EXT2) are major causative genes in MO." (PMID 26961984, 2016). "To further analyze the mutations in EXT1, we gathered all of the mutations in its 11 exons from the Multiple Osteochondroma Mutation Database." (PMID 25421355, 2015). "Evidence in support of this comes from previous studies showing that Ext1 deficiency leads to the formation of osteochondroma-like lesions adjacent to growth plate cartilage." (PMID 26091072, 2015). "Decreased levels of HS due to mutations in EXT1 or EXT2 also lead to a skeletal abnormality resulting in one of the most common benign bone tumours in young adults – osteochondroma." (PMID 24628984, 2014). "MO is known as a genetic syndrome manifesting by the formation of multiple osteochondromas caused by the inactivation of EXT1 or EXT2." (PMID 22253766, 2012). "In osteochondromas, the cartilage cells of the tumor cap are heterogeneous regarding to the mutation status in EXT1 or EXT2, with a mixture of homozygous and heterozygous EXT-inactivated cells." (PMID 21703028, 2011). "Smaller single or multi-exon rearrangements in EXT1 or EXT2 cause a phenotype of multiple osteochondromas only." (PMID 21703028, 2011).
Osteochondroma (continued). "In osteochondromas and peripheral chondrosarcomas the expression of EXT1 and/or EXT2 is decreased, corresponding to the mutation status." (PMID 18271966, 2008). "Loss of the remaining EXT1 wildtype allele has been demonstrated in the cartilage cap of osteochondromas from MO patients." (PMID 18271966, 2008). "Mutations in EXT1/2 have been implicated in osteochondroma formation; however, secondary peripheral chondrosarcomas often retain functional EXT alleles, suggesting that malignant progression may involve EXT-independent mechanisms." (PMID 40867318, 2025). "Meanwhile, EXT1 is primarily recognized for its role in hereditary multiple exostoses (osteochondromas), and the potential relevance of EXT1 mutations in CRC remains unclear." (PMID 40565166, 2025). "Osteochondromas may also be associated with multiple hereditary exostoses linked to mutations in the EXT1 and EXT2 genes." (PMID 41220449, 2025). "According to this hypothesis, probands may harbor an additional somatic loss-of-function variant in the EXT1 gene, contributing to osteochondroma formation." (PMID 39192890, 2024). "Interestingly, there is a decrease in perlecan in the matrix of EXT1-associated osteochondromas, supporting a connection between HSPGs, FN, and the etiology of HME." (PMID 34890641, 2022). "Mutations in EXT1 have been linked to skeletal abnormalities and osteochondromas." (PMID 34890641, 2022). "It is possible that EXT1 is functionally associated with FBXW7, presumably through priming kinases and substrates like N1‐ICD and therefore, mutational events affecting the EXT1 or FBXW7 gene can significantly affect the pathogenesis in osteochondroma patients through the NOTCH pathway." (PMID 33822486, 2021). "Further clinical testing to determine the cause of the patient's multiple osteochondromas was unrevealing despite extensive profiling of the most likely causative genes, EXT1 and EXT2, including mutation screening by direct sequence analysis and multiplex ligation‐dependent probe amplification." (PMID 30632316, 2019). "As for its contribution on bone diseases, in 2013, a mutation screening for EXT1 in Chinese population confirmed that such gene may be functional related with a specific bone disease, osteochondromas, validating the efficacy and accuracy of our prediction." (PMID 29258237, 2017). "We also asked whether conditional Ext1 ablation would alter the cranial base and cause osteochondroma formation in mice and whether osteochondroma formation was amenable to drug treatment." (PMID 28445472, 2017). "Although Ext1/2-deficient mice develop multiple bony lesions with features similar to osteochondromas in HME patients, the underlying mechanisms remain unclear." (PMID 26091072, 2015). "In addition, we can infer that over-expression of EXT1 may cause a disorder of endochondral ossification signaling cascades, leading to osteochondroma." (PMID 31842965, 2019). "Three genes (TRPS1, RAD21, and EXT1) are considered responsible for the most common clinical features, which include facial dysmorphism, ectodermal and skeletal anomalies, osteochondromas, and cognitive impairment." (PMID 41683676, 2026). "Interestingly, EXT1/2 mutations seem to be less frequently detected in sporadic secondary peripheral chondrosarcomas than expected based on the assumption that they originate in sporadic osteochondromas, in which the homozygous inactivation of EXT1 is found in about 80% of our cases." (PMID 36674874, 2023). "In this work, we identified through population differentiation analysis that an osteochondroma-related gene, EXT1, exhibits a relatively high level of population differentiation between Chinese domestic geese and swan geese." (PMID 37106733, 2023). "The other candidate gene was an osteochondroma-related gene, Exostosin glycosyltransferase 1 (EXT1), which also showed a relatively high level of population differentiation." (PMID 37106733, 2023).
Osteochondroma (continued). "Genetic variants of these genes cause multiple exostoses, osteochondromatosis, or EXT1/EXT2-CDG, which are autosomal dominant O-linked glycosylation disorders characterized by the formation of multiple cartilage-capped tumors (osteochondromas)." (PMID 35955863, 2022). "Loss-of-function mutations in EXT1 and EXT2, the enzymes responsible for HS synthesis, cause HME, an autosomal dominant disorder that is characterized by osteochondromas." (PMID 34890641, 2022). "Compound heterozygous Ext1+/−; Ext2+/− deletion mice and conditional Ext1 knockout mice display multiple osteochondromas and closely resemble human HME." (PMID 33632255, 2021). "Regarding solitary osteochondromas, EXT1 homozygous deletions are found to be confined to the cartilaginous cap in sporadic cases, confirming that EXT1 is required for osteochondroma development." (PMID 31842965, 2019). "The more significant positive rate of EXT1 in condylar osteochondroma implied differential biological characteristic as compared to condylar hyperplasia." (PMID 31842965, 2019). "The positive rate of EXT1 expression in the condylar osteochondroma group was significantly higher than was found in condylar hyperplasia." (PMID 31842965, 2019). "EXT1 was mainly expressed in the cartilage layer, and there was a higher positive rate of EXT1 in the condylar osteochondroma group (p = 0.0366, p < 0.5)." (PMID 31842965, 2019). "The higher EXT1 positive rate in condylar osteochondroma implied different biological characteristics as compared to condylar hyperplasia." (PMID 31842965, 2019). "On the other hand, aberrant distribution of HSPG was recently described in chondrosarcomas and osteochondromas in the presence of normal expression of EXT genes and in EXT1 deletion, respectively." (PMID 30544937, 2018). "We previously showed there was broad, ectopic and excess BMP signaling in perichondrium of long bone growth plates in conditional Ext1-null mice that was followed by ectopic cartilage tissue formation and osteochondroma development." (PMID 28445472, 2017). "Systemic administration with LDN-193189 effectively inhibited osteochondroma growth in conditional Ext1-mutant mice." (PMID 28445472, 2017). "Evidence has been provided that EXT1 functions as a typical tumor suppressor gene, that is, both copies are functionally inactivated in osteochondroma cells, with both inactivating events being somatic in solitary, non-hereditary osteochondromas." (PMID 26043835, 2015). "This is supported by the fact that a recombination rate of only 6%–15% is sufficient to induce the formation of osteochondroma-like lesions in Ext1f/f mice, in which osteochondroma-like lesions contain both Ext1-null and wild-type chondrocytes." (PMID 26091072, 2015). "EXT1-null embryonic stem cells also appear to have impaired differentiation hematopoietic lineages, while osteochondromas exhibit impaired vascularisation." (PMID 24628984, 2014). "Loss of heterozygosity (LOH) of EXT1 and/or EXT2 is shown in some solitary osteochondromas and HMEs." (PMID 21403832, 2011). "Although it is quite clear that inactivation of EXT1 and EXT2 encourages osteochondroma development, the exact molecular trigger causing its malignant transformation is unclear." (PMID 21437176, 2011). "In seven out of eight solitary osteochondromas, homozygous deletions of EXT1 are found further supporting the two-hit model." (PMID 18271966, 2008). "Although the extent of deletion of the Ext1 gene was mild, downregulation of the osteoarthritis pathway may be responsible for the mechanism of osteochondroma formation in AcanCreER;Ext1f/f mice." (PMID 39062860, 2024). "In MO pathogenesis, germline heterozygous mutations in EXT1 or EXT2 are not sufficient to cause osteochondroma formation." (PMID 35103870, 2022).
Osteochondroma (continued). "A search for all Dutch patients registered with both osteochondroma and kidney biopsy (n = 39) showed that an EXT1 or EXT2 mutation does not necessarily lead to specific glomerular morphological phenotypic changes." (PMID 35103870, 2022). "EXT1 and EXT2 variants in the 22 Chinese families with multiple osteochondromas." (PMID 33414810, 2020). "In addition, a higher EXT1 positive rate in condylar osteochondroma implied different biological characteristics in condylar osteochondroma when compared to condylar hyperplasia." (PMID 31842965, 2019). "While mosaic mutations and deletions of EXT1 and EXT2 have been reported in the context of multiple osteochondromas, to our knowledge, this is the first time that transcriptomics technologies have been used to diagnose a patient via fusion transcript analysis in the congenital disease setting." (PMID 30632316, 2019). "Thus, we detected that expression of EXT1 in both groups to determine the importance of the difference between condylar osteochondroma and condylar hyperplasia, and to preliminarily explore the mechanism of osteochondroma." (PMID 31842965, 2019). "The finding in a subset of osteochondromas of cytogenetic aberrations, mainly 8q deletions, as well as biallelic inactivation of the EXT1 (located in 8q24) or EXT2 (located in 11p11) gene in cells of the cartilage cap supports a neoplastic nature of the tumors." (PMID 26043835, 2015). "Interestingly, our population differentiation analysis followed by an extended genotype analysis in an additional population suggested that two intronic SNPs in EXT1, an osteochondroma-related gene, may plausibly be sites responsible for knob." (PMID 37106733, 2023). "However, the observation that LOH and clonal rearrangement at 8q24 (EXT1 locus) are as frequent in non-hereditary osteochondromas as EXT1 gene mutations in patients with hereditary osteochondromas." (PMID 31842965, 2019). "This study attempted to compare the histological features of mandibular condylar hyperplasia and condylar osteochondroma using hematoxylin-and-eosin (H&E) staining, and immunohistochemistry staining of PCNA and EXT1 with quantitative analysis method." (PMID 31842965, 2019). "Our data on EXT1 and EXT2 from case 2 are in agreement with previously reported expression data from osteochondromas in that they showed low expression levels." (PMID 26043835, 2015). "Several mice models have been developed to study the role of EXT1 or EXT2 in bone and osteochondroma formation." (PMID 24628984, 2014). "In a reciprocal manner, LDN-193189 could be more effective if given prior to osteochondroma initiation or even chronically and if it were to be tested in less aggressive HME mouse models, such as single Ext1+/- or double heterozygous Ext1+/-;Ext2+/- mice." (PMID 28445472, 2017).